NLRP3 (NLR family pyrin domain containing 3)
Diseases named in the same sentence as NLRP3 in open-access papers (continued):
Sharing a sentence is not in itself a finding about the gene and the disease.
atherosclerosis (continued). "Third, although our in vitro and in vivo experiments demonstrate that sno-circCNOT1 promotes atherosclerosis progression through the LMNA/METTL14 /NLRP3 axis, its clinical significance remains to be fully elucidated." (PMID 41510160, 2026). "Beyond atherosclerosis, activation of the NLRP3 inflammasome has been shown to contribute to myocardial ischemia–reperfusion injury and chronic heart failure." (PMID 41590246, 2026). "In this pathological context, the NLRP3 inflammasome plays an important role in the pathogenesis of atherosclerosis, being involved in endothelial cell damage and in the link between lipid metabolism and the inflammatory response." (PMID 41590246, 2026). "The NOD-like Receptor Pyrin Domain-Containing 3 (NLRP3) inflammasome has emerged as a crucial mediator of inflammation in atherosclerosis, with caspase recruitment domain family member 8 (CARD8) acting as a key regulatory component." (PMID 41659085, 2026). "Foam cells, derived from macrophages and vascular smooth muscle cells, release DAMPs in advanced lesions, which maintains NLRP3 inflammasome activation and contributes to atherosclerosis progression." (PMID 41590246, 2026). "TET2 mutations in particular enhance expression and release of pro‐inflammatory cytokines such as IL‐1β, activating the NLRP3 inflammasome thereby driving atherosclerosis and NLRP3‐inhibition rescues adverse remodeling and cardiac hypertrophy." (PMID 41546123, 2026). "These mutant cells exhibit amplified IL-1β production, enhanced NLRP3-inflammasome activity, and increased chemokine signalling, thereby accelerating atherosclerosis, insulin resistance, and vascular inflammation." (PMID 41665140, 2026). "In conclusion, our findings demonstrate that shear-sensitive sno-circCNOT1 promotes endothelial pyroptosis and inflammation via the LMNA/METTL14/NLRP3 axis, thereby accelerating atherosclerosis progression." (PMID 41510160, 2026). "NLRP3 is an important mediator of sterile inflammatory diseases, including gout, type 2 diabetes, and vascular diseases such as atherosclerosis." (PMID 40835597, 2025). "ZTLT has been shown to limit foam cell formation and reduce lipid levels by preventing vascular inflammation and macrophage pyroptosis through the Piezo1/NLRP3 signaling pathway, thus slowing the progression of atherosclerosis." (PMID 40099271, 2025). "NLRP3 is a classic inflammasome, which can participate in the inflammatory response in atherosclerosis." (PMID 41462995, 2025). "These molecules further activate the NLRP3 inflammasome, promoting the release of inflammatory factors, thereby exacerbating neurovascular inflammation and promoting the development of atherosclerosis." (PMID 40491586, 2025). "This inhibition prevents the interaction between ASC and NLRP3, resulting in the suppression of endothelial cell pyroptosis in the aortic root and the amelioration of atherosclerosis." (PMID 40307577, 2025). "FOXP1 transrepresses NLRP3 inflammasome components, and its targeted deletion in ECs intensifies atherosclerosis in Apoe−/− mice." (PMID 39949978, 2025). "Inflammatory conditions such as gout, type 2 diabetes, obesity, atherosclerosis, and Alzheimer’s disease exhibit aberrant Nlrp3 activation as a key contributor to disease pathogenesis." (PMID 40002829, 2025). "Our results revealed that PEMFs mitigate plaque formation and delay the progression of atherosclerosis by suppressing NLRP3 inflammasome activation." (PMID 41309549, 2025). "The study also highlights the NLRP3 inflammasome as a potential therapeutic target due to its role in atherosclerosis." (PMID 41377919, 2025). "PEMFs were found to effectively inhibit the activation of the NLRP3 inflammasome, reduce plaque formation, and delay the progression of atherosclerosis." (PMID 41309549, 2025).
atherosclerosis (continued). "Pro-inflammatory pathways, including IL-1β/IL-6 signaling, NLRP3 inflammasome activation, and JAK2-mediated thrombo-inflammation, explain its role in atherosclerosis, metabolic dysfunction, and thrombotic risk, highlighting druggable targets for prevention." (PMID 41516113, 2025). "It has been reported that inhibition of NLRP3 activation can prevent the progression of atherosclerosis by reducing macrophage inflammation and pyroptosis." (PMID 41462995, 2025). "Another circRNA, hsa_circ_0043621, contributes to the pathogenesis of atherosclerosis by acting as a molecular sponge for miR-223-3p, increasing NLRP3 expression." (PMID 40307577, 2025). "Studies have indicated that the NLRP3 inflammasome in animal models of hypertension can promote atherosclerosis and myocardial injury by facilitating immune cell infiltration, triggering oxidative stress, and inducing vascular endothelial dysfunction." (PMID 41194915, 2025). "Consistently, Zhao and colleagues have demonstrated that SAB reverses atherosclerosis and inflammation by suppressing nuclear translocation of NF-κB and NLRP3 inflammasome activation in TNF-α-treated human umbilical vein endothelial cells." (PMID 40722987, 2025). "These actions highlight colchicine’s broad, multi-target inhibition of NLRP3 inflammasome-driven inflammation, supporting its therapeutic potential in inflammatory-driven diseases and atherosclerosis." (PMID 41010600, 2025). "Given its role in atherosclerosis development, the NLRP3 inflammasome remains a promising therapeutic target, with novel inhibitors under investigation." (PMID 41377919, 2025). "Its mechanisms of action target key inflammatory pathways involved in atherosclerosis, particularly through inhibition of neutrophil activation, NLRP3 inflammasome assembly, and modulation of endothelial dysfunction." (PMID 41010600, 2025). "Subsequent studies have found that MCC950 has a good therapeutic effect on NLRP3 related diseases such as enteritis and atherosclerosis." (PMID 40362256, 2025). "NLRP3 is a key mediator of the post-MI inflammatory response and is involved in the development of atherosclerosis, MI, and heart failure." (PMID 40332346, 2025). "These in vivo results demonstrate that TRPV4 hyperactivation exacerbates atherosclerosis by promoting inflammation and NLRP3 activation, whereas its inhibition confers strong protection, establishing TRPV4 as a key mechanistic target for treatment." (PMID 41309549, 2025). "Recent studies highlight the role of the NOD-like receptor family pyrin domain containing 3 (NLRP3) inflammasome in atherosclerosis and its progression to CVD." (PMID 41343565, 2025). "The NLRP3 inflammasome is a crucial regulator of inflammation, myocarditis, and atherosclerosis, and its activation leads to IL-1β secretion, promoting myocardial inflammation and fibrosis." (PMID 40724868, 2025). "Dysregulation of the NLR-family pyrin domain containing 3 (NLRP3) inflammasome has emerged as a key contributor to the pathogenesis of numerous human diseases including atherosclerosis, gout, multiple sclerosis, Alzheimer’s disease, and several cancers." (PMID 39653810, 2025). "ASC and caspase-1, as key adaptor proteins of the NLRP3 inflammasome, exhibit sharply increased levels during the progression of atherosclerosis." (PMID 39936975, 2025). "The activation of NLRP3 in endothelial cells (ECs) represents a key event leading to endothelial damage, and its impact on atherosclerosis is primarily mediated by the effector cytokine IL-1β." (PMID 41194915, 2025). "While moderate activation contributes to infection resistance and cellular homeostasis, excessive NLRP3 inflammasome activity can drive severe inflammatory pathologies such as inflammatory bowel disease, gout, and atherosclerosis." (PMID 41463800, 2025). "In murine atherosclerosis models, it suppressed inflammasome assembly, enhanced NLRP3 ubiquitination, and limited plaque progression." (PMID 40648980, 2025).
atherosclerosis (continued). "In this review, we attempt to summarize the recent findings about the role of NLRP3 in the pathogenesis of tumors and inflammatory diseases such as diabetes, Alzheimer disease, and atherosclerosis." (PMID 40671401, 2025). "Our results demonstrate that GC potentiates CMA activity in macrophages, leading to promoted degradation of the NLRP3 inflammasome, suppression of NLRP3/IL-1β-mediated inflammation, and ultimately conferring protection against atherosclerosis." (PMID 41282617, 2025). "Monosodium urate crystals in gout and cholesterol crystals in atherosclerosis directly activate the NLRP3 inflammasome, which intensifies local inflammation." (PMID 40307577, 2025). "This research highlights the potential for pharmacologically activating CMA as a strategy to enhance NLRP3 inflammasome degradation, thus reducing inflammation and slowing atherosclerosis." (PMID 40244103, 2025). "Silencing NLRP3 or using the antioxidant N-acetyl-L-cysteine (NAC) reduced inflammasome activation and atherosclerosis, indicating that NLRP3 activation is a key mediator of HHcy-induced vascular inflammation." (PMID 39898976, 2025). "The inflammatory response in atherosclerosis involves multiple pro-inflammatory pathways beyond the NLRP3 inflammasome." (PMID 39657321, 2025). "Previous studies have demonstrated that miltefosine can ameliorate atherosclerosis by promoting cholesterol efflux from macrophages, inhibiting NLRP3 inflammasome activation, and enhancing autophagy and mitophagy." (PMID 40292315, 2025). "Nonimmune cardiac injury, such as MI, can trigger inflammation, and several studies support the role of NLRP3 in atherosclerosis and ACS." (PMID 41377919, 2025). "Another study demonstrated that melatonin prevented the progression of atherosclerosis by inducing mitophagy and inhibiting activation of the NLRP3 inflammasome, which was mediated by the Sirt3/FOXO3a/Parkin signaling pathway." (PMID 41300435, 2025). "Given its central role in inflammatory processes, the NLRP3 inflammasome has emerged as a promising therapeutic target for atherosclerosis intervention." (PMID 40689206, 2025). "Within the context of atherosclerosis, cholesterol crystals (CCs) represent a major endogenous activator of the NLRP3 inflammasome, inducing a robust inflammatory response." (PMID 41010600, 2025). "Experimental studies using in vitro and in vivo models of atherosclerosis have further elucidated the role of NLRP3 inflammasome in diabetic macrovascular disease." (PMID 40648980, 2025). "Nevertheless, CP-456773/MCC950 remains a prevalent NLRP3 inhibitor in both in vitro and in vivo studies of numerous diseases, including diabetes, atherosclerosis, myocardial infarction, neurodegenerative diseases, and myeloid malignancies." (PMID 39875995, 2025). "Increases SOD and GSH in serum in diseased mice.Suppresses the expression of IL-6, TNF-α, ICAM-1, VCAM-1 and NLRP3.Ameliorates atherosclerosis." (PMID 41300435, 2025). "NLRP3 inflammasome involvement has been observed in cardiovascular diseases (CVDs), including hyperlipidemia, obesity, and atherosclerosis." (PMID 40807276, 2025). "More recently, tranilast increased NLRP3 ubiquitination in two murine models of atherosclerosis, which inhibited the assembly of the NLRP3 inflammasome and, as a result, slowed the development and spread of atherosclerotic plaques." (PMID 40079000, 2025). "In this study, we investigated the effect of β-sitosterol on HFD-induced atherosclerosis in ApoE−/− mice and explored the underlying mechanisms involving the MAPK/Nrf2/NLRP3 pathway." (PMID 40966231, 2025). "The activation of NLRP3 is one of the key factors of atherosclerosis and is related to many chronic diseases." (PMID 40278349, 2025). "The NLRP3 inflammasome/IL-1β-dependent inflammatory response serves as a critical factor and key trigger in exacerbating atherosclerosis (AS), whereas chaperone-mediated autophagy (CMA) recognizes and degrades the NLRP3 inflammasome." (PMID 41282617, 2025).
atherosclerosis (continued). "In a TET-2 mutated CH model, for example, monocyte-macrophages are activated with up-regulation of IL-1β signaling, mediated by the activated NLRP3 inflammasome, accelerating atherosclerosis development and maladaptive cardiac remodeling in mice." (PMID 40355940, 2025). "Pyroptosis, a form of programmed inflammatory cell death mediated by the NLRP3 inflammasome, has recently emerged as a critical mechanism in the pathogenesis of atherosclerosis and plaque rupture." (PMID 41377919, 2025). "The NLRP3 inflammasome has recently been considered a critical modulator of cardiovascular pathology, including atherosclerosis (AS)." (PMID 40564905, 2025). "Both colchicine and dapagliflozin can decelerate the progression of atherosclerosis through the inhibition of NLRP3 inflammasome activation." (PMID 41194915, 2025). "NLRP3 is a key pyroptotic protein, and the decrease in its expression contributes to the inhibition of EC pyroptosis, thereby alleviating atherosclerosis." (PMID 40861271, 2025). "Collectively, these results demonstrate that NLRP3 is a critical driver of the pathogenesis of atherosclerosis and that PEMFs confer protection primarily through the inhibition of NLRP3-mediated inflammation and pyroptosis." (PMID 41309549, 2025). "Colchicine, a broad-spectrum anti-inflammatory agent that inhibits the NLRP3 inflammasome, has emerged as a promising therapy for atherosclerosis prevention." (PMID 40076813, 2025). "The seminal role of the NLRP3 inflammasome and the IL‐1β pathway in atherosclerosis has recently been reviewed in detail." (PMID 40055964, 2025). "It was established that, compared to non-smokers, heavy smokers with coronary artery disease display activation of the NLRP3 inflammasome which facilitates the progression of atherosclerosis." (PMID 40216765, 2025). "Neuroinflammation-driven disorders, including atherosclerosis, neuropathic pain, substance use, and stress-related syndromes, show how sex influences NLRP3 inflammasome expression and activity with downstream effects on cognition and behavior." (PMID 41357236, 2025). "The present study demonstrates that AT-I protects against nicotine-induced macrophage pyroptosis and atherosclerosis by inhibiting the TLR4/ROS/TXNIP/NLRP3 signaling pathway." (PMID 40422906, 2025). "It has recently been established that the excessive activation of the NLRP3 inflammasome mediates inflammatory responses and has a role in the development and initiation of atherosclerosis." (PMID 39844544, 2025). "Inhibition of the NLRP3 inflammasome and pyroptosis has been shown to mitigate the harmful effects of oxidative stress in atherosclerosis, further underscoring the therapeutic potential of autophagic modulation in treating cardiovascular disease." (PMID 40244103, 2025). "ox-LDL has been implicated in aberrant activation of NLRP3, which, in turn, activates GSDMD and exacerbates atherosclerosis in both mouse models and humans." (PMID 40244103, 2025). "On the basis of our findings that PEMFs inhibit atherosclerosis via the NLRP3 inflammasome, we next investigated how this external stimulus influences specific intracellular processes." (PMID 41309549, 2025). "Various studies reported that NLRP3 plays a crucial role in atherosclerosis, vascular remodelling and facilitates VSMC pyroptosis through autophagy induction and downregulation of ROS generation." (PMID 41335598, 2025). "In conclusion, our study demonstrated that β-sitosterol alleviated HFD-induced atherosclerosis in ApoE−/− mice by regulating the MAPK/Nrf2/NLRP3 pathway." (PMID 40966231, 2025). "We therefore consider NLRP3 a promising therapeutic target in atherosclerosis, as it combines classic inflammasome inhibition—reducing IL-1β and IL-18 release—with direct anti-proliferative effects on plaque macrophages." (PMID 40956333, 2025). "Collectively, these data support NLRP3 and downstream IL-1 family signaling as actionable pathways in CHIP-associated atherosclerosis." (PMID 41516113, 2025).
atherosclerosis (continued). "In atherosclerosis, for instance, the chronic, low-grade activation of the NLRP3 inflammasome within macrophages and endothelial cells is unequivocally pro-atherogenic, promoting lipid accumulation, plaque inflammation, and instability." (PMID 41488670, 2025). "The NLRP3 inflammasome plays a critical role in the release of mature IL-1β, a key factor in the progression of atherosclerosis." (PMID 39936975, 2025). "Among inflammasomes, NLRP3 is the most extensively studied due to its role in various diseases, including DM, atherosclerosis, gout, and neurodegeneration." (PMID 40648980, 2025). "For instance, mice with TET2 knockout bone marrow transplants showed accelerated atherosclerosis, activated through the NLRP-3/IL-1β inflammasome pathway and upstream IL-6 signaling." (PMID 40355940, 2025). "The mechanisms of pyroptosis and atherosclerosis overlap, where oxidative stress not only triggers cell damage but also activates the NLRP3 inflammasome, enhancing the inflammatory response and promoting pyroptosis." (PMID 40478791, 2025). "TET2 deletion promotes the occurrence of cardiovascular disorders such as cardiac failure and atherosclerosis by the activation of IL‐1β/NLRP3 inflammasome through macrophages." (PMID 40607626, 2025). "It would be advantageous to target the NLRP3 inflammasome in order to stop atherosclerosis from progressing." (PMID 39844544, 2025). "The NLRP3 inflammasome–IL-1β axis plays a particularly critical role in atherosclerosis (AS), where oxidized low-density lipoprotein (oxLDL) activates NLRP3, leading to IL-1β release, plaque instability, and thrombosis." (PMID 41394800, 2025). "Cigarette smoke triggers the activation of the NLRP3 inflammasome in atherosclerosis, engaging monocytes, macrophages, and foam cells in the process." (PMID 40093753, 2025). "The NLRP3 inflammasome is a multiprotein complex that serves as a critical mediator in the pathogenesis of cardiovascular conditions, including atherosclerosis, myocardial ischemia-reperfusion injury, and heart failure." (PMID 40513070, 2025). "Research indicates that components of the NLRP3 inflammasome are significantly elevated in carotid atherosclerotic plaques, highlighting the critical role of NLRP3 in the pathogenesis of atherosclerosis." (PMID 41194915, 2025). "NLRP3 inflammasome-mediated activation of IL-1β secretion has become an important component of the inflammatory process in atherosclerosis." (PMID 40867876, 2025). "For instance, homocysteine, a byproduct of methionine metabolism that accumulates in kidney dysfunction, can trigger NLRP3 activation in vascular smooth muscle cells and endothelial cells, promoting atherosclerosis." (PMID 41488670, 2025). "Phagocytosed crystalline structures, such as cholesterol crystals in atherosclerosis or monosodium urate crystals in gout, destabilize lysosomes, release cathepsins and robustly trigger NLRP3 activation." (PMID 41488670, 2025). "It is interesting to point out that, in models of diabetes, liver disease and atherosclerosis, physical exercise decreases the activation of NLRP3." (PMID 39932994, 2025). "Our previous research showed that 5-DR suppressed atherosclerosis via inhibiting NLRP3 inflammasome-related inflammation and modulating cholesterol transport." (PMID 39981175, 2025). "A recent study revealed that TET2 deficiency, an epigenetic regulator of DNA methylation, promoted JNK activation and BRCC3-mediated DUB of the NLRP3 inflammasome, accelerating atherosclerosis and the formation of neutrophil extracellular traps." (PMID 40307577, 2025). "To this end, we used a variety of Medical Subject Headings (MeSHs) and free-text keywords, including “inflammasome”, “NLRP3”, “cardiovascular diseases”, “atherosclerosis”, “heart failure”, “pericarditis”, “pyroptosis”, “IL-1β”, “IL-18”, and “targeted therapy”." (PMID 40564905, 2025).